INS (insulin)
Diseases named in the same sentence as INS in open-access papers (continued):
Sharing a sentence is not in itself a finding about the gene and the disease.
Hypoglycemia (continued). "In addition, more recently pumps with automated insulin delivery (AID) systems, also known as closed loop, have been introduced in the clinical setting, which could further enhance the likelihood of reaching the glycemic targets while mitigating the frequency of hypoglycemia." (PMID 37739421, 2023). "Thus, we may suggest that BPC 157 recovered both insulin pathways (insulin and glucagon release are under KATP channel control as well as under the control of hypothalamus-brain stem hypoglycemia-induced vagal signaling) during hypoglycemia and regained brain–gut function integrity." (PMID 37242459, 2023). "In the short term, a lower insulin response prevents hypoglycemia and inappropriate increases in non-esterified fatty acids (NEFA) and anti-insulin hormone responses, often seen during the late postprandial period after the intake of refined carbohydrates." (PMID 37242267, 2023). "Treating with Gla-100 based basal insulin therapy in T2DM with renal failure is safe and efficacious in decreasing glycemic parameters without significant weight gain or hypoglycemia." (PMID 36624650, 2023). "Therefore, large doses of insulin may be required in humans, and it has been reported that a high-dose oral insulin (67.5 mg daily) induced an immune response in genetically at-risk healthy children, which may be protective for T1DM, and no adverse event, such as hypoglycemia, was detected." (PMID 36719009, 2023). "Hypoglycemia has not yet been identified in these models, which means that VIP induces insulin secretion in a glucose-dependent manner." (PMID 36204104, 2022). "In this study, symptomatic hypoglycaemia and severe hypoglycaemia did not occur, but the TBR < 3.9 mmol/L and TBR < 3.0 mmol/L were significantly higher in the premixed insulin group than in the basal insulin group." (PMID 35574003, 2022). "While basal insulin, if appropriately dosed, should not have to be held if a patient is temporarily NPO, holding parameters can also be specified for added hypoglycemia preventive measures." (PMID 35917098, 2022). "In the final mesh meta-analysis, the numbers for fasting C-peptide, 2 h postprandial C-peptide, fasting insulin, 2 h postprandial insulin, HOMA-β, and the incidence of hypoglycemia were small, which did not meet the data requirements of the mesh meta-analysis." (PMID 36015100, 2022). "Severe hypoglycaemia and IAH (a key secondary endpoint) are not trivial side-effects of insulin therapy." (PMID 35484106, 2022). "One study showed a 3% lower rate of hypoglycemia < 65 mg/dL (3.6 mmol/L) with PLGS, compared to CSII with RT-CGM without automated insulin suspension." (PMID 36275049, 2022). "PACAPVMH neurons are GI and, although activating them with a stimulatory DREADD inhibits insulin (which is the first CRR to falling glucose levels), this manipulation does not release glucagon (a CRR to a deeper hypoglycemia) or affect basal glucose levels." (PMID 34265067, 2021). "Recent randomized controlled trials in intensively insulin-treated T2D demonstrated the efficacy and safety of real-time CGM (rtCGM) in reducing glycated hemoglobin without increasing hypoglycemia." (PMID 33534631, 2021). "After glimepiride was replaced with pioglitazone (30 mg/day) for 3 months, his glucose control did not change but his triglyceride, insulin, and inflammatory marker levels decreased, with no hypoglycemia or reduced eGFR." (PMID 34764936, 2021). "The ratio of insulin/glucose was 0.62, and the response of cortisol, insulin-like growth factor-1 (IGF-1), and glucagon to hypoglycemia was not significant." (PMID 34032745, 2021). "Both acute insulin-induced hypoglycemia and glucose deprivation by 2DG activated GHRH neurons, and this effect was absent with repeated 2DG-induced and repeated insulin-induced hypoglycemia." (PMID 33148883, 2020). "BCTE consumed with a normal diet by KK-Ay mice induced hypoglycemia and modulated basal GLP-1 concentrations without affecting plasma insulin levels, food intake, or BW." (PMID 32825710, 2020).
Hypoglycemia (continued). "A systematic review and meta-analysis revealed that metformin is better than insulin in reducing both, maternal weight gain during pregnancy and the frequency of PIH, with no changes in the frequency of hypoglycemia and preeclampsia." (PMID 32625081, 2020). "Nonetheless, the insulin delivery method did not influence time spent in hypoglycemia, the group with MDI registering similar results with the insulin pump therapy group at the end of the intervention." (PMID 33023137, 2020). "It is important to note that at 30 min following insulin injection, the MTII treated diabetic mice did not exhibit hypoglycemia (∼120 mg/dl)." (PMID 30503832, 2019). "There were no episodes of hypoglycemia and there was no significant change in FEV1 following treatment with inhaled insulin (100 ± 5 vs. 96 ± 7 % of predicted)." (PMID 31470605, 2019). "In summary, these data show that the increased glucagon counter-regulatory response to hypoglycemia in mutant I366F mice is not simply due to altered GCK activity (and insulin release/glycemia) in pancreatic β-cells." (PMID 30146176, 2018). "All patients required insulin infusion during both the IIT and the CIT (control) and none of them had hypoglycemia episodes (i.e., blood glucose < 3.9 mmol/L)." (PMID 29300728, 2018). "Both treated and untreated mice had normal blood sugars, demonstrating, that unlike insulin, the BCG-induced metabolic shift to aerobic glycolysis does not induce hypoglycemia and the increased glucose utilization by BCG is receptor regulated." (PMID 29951281, 2018). "After insulin injection, blood glucose levels of 4-MEI-fed animals dropped significantly and did not recover from severe hypoglycaemia (level 2; blood glucose < 54 mg/dl) until 60 minutes." (PMID 30451881, 2018). "Notably, although women in the CGM group showed a greater decrease in hypoglycaemia avoidance behaviour than did women in the control group, they did not have less worry, suggesting that automated insulin delivery might be more effective for reduction in maternal fear of hypoglycaemia." (PMID 28923465, 2017). "None of the PROS patients had fasting hypoglycaemia; however, three patients with MCAP had low or undetectable plasma insulin concentrations with normal or low-normal fasting glucose (P19, P20, P22)." (PMID 28566443, 2017). "In the hippocampus of a rat model of insulin-induced hypoglycemia, administration of D-BHB, and not acetoacetate, reversed hypoglycemia-induced lipid peroxidation." (PMID 28335557, 2017). "Acute complication (DKA and severe hypoglycemia events), TDD insulin, and weight change were not significant in both groups." (PMID 30291064, 2017). "Our study showed as follows; accompanied with insulin, switching from DPP-4 inhibitors to dapagliflozin maintained an equivalent glucose fluctuation and all-day and nocturnal hypoglycaemia prevalence without significant insulin dosage change." (PMID 28725273, 2017). "The goal of insulin therapy with either MDI or CSII is to achieve fasting, preprandial and postprandial, and overnight glucose levels in the target range without hypoglycemia." (PMID 27337958, 2016). "As previously reported in meta-analyses, the rate of hypoglycemia was not higher in T2DM patients treated with the DPP-4 inhibitors, even in patients already undergoing treatment with insulin or a sulfonylurea." (PMID 26500706, 2015). "Additionally, during the 72-hour glucose fasting test, the patient did not experience substantial symptoms of hypoglycemia, suggesting that the relative hypoglycemia during the fast may have been physiologic, with incomplete suppression of insulin and C-peptide." (PMID 26346767, 2015). "Hypoglycemia did not occur during or after HIIE and CON when using ultra-long-acting insulin and applying our methodological approach for exercise prescription." (PMID 26317981, 2015).
Hypoglycemia (continued). "While insulin analogues may or may not be better than human insulins, clinical practice (the specialist opinion) clearly shows they provide great benefits, especially and maybe only for the small percentage of patients that experience frequent, severe or nocturnal hypoglycemia." (PMID 25964802, 2015). "The number of episodes of hypoglycemia less than 40 mg/dL was low in both groups, but not statistically significant higher in the group with NPH and regular insulin." (PMID 26697118, 2015). "Subsequent studies evaluating the role of insulin therapy in the ICU either failed to confirm these results, or were terminated early due to high hypoglycemia rates." (PMID 24886864, 2014). "However, there exist patient barriers such as fear of hypoglycemia, injections and weight gain, as well as physicians’ concerns such as reluctance to prescribe insulin, result in non-adherence to initiation and intensification of insulin treatment, leading to delayed use of effective therapy." (PMID 24528773, 2014). "Patients with hypoglycemia and HCC have low concentrations of insulin and C-peptide, which rules out insulin overproduction as a cause." (PMID 25202415, 2014). "Presumably, under insulin-stimulatory conditions, intra-islet insulin action may not be able to efficiently exert suppressive effects on α-cell secretion, whereas under glucagon-stimulatory conditions, intra-islet hyperinsulinemia prevents the glucagon response to hypoglycemia." (PMID 23316165, 2012). "There was no insulin in the patient's TPN and the last dose of insulin aspart (4 units) had been administered subcutaneously 5 days before hypoglycaemia occurred." (PMID 18644072, 2008). "Frequency of hypoglycaemia,a hypokalaemiab and hyperkalaemiac (%) in diabetic ketoacidosis (DKA) episodes with vs. without fixed rate intravenous insulin infusion rate reduction by 50% initial rate when blood glucose <14 mmol/L during DKA across hospital sites A‐E." (PMID 39928758, 2025). "Importantly, unlike insulinomas, these episodes typically do not coincide with elevated insulin levels but rather result from increased secretion of IGF‐2, leading to hypoglycemia." (PMID 40550558, 2025). "Insulin lispro-aabc achieved faster onset and earlier glucose-lowering effects than conventional insulin lispro, with trials showing reduced postprandial glucose (PPG) levels without significantly different hypoglycemia risks." (PMID 39766270, 2024). "Hence, in contrast to intense, early onset insulin therapy, inceptor-mediated improvement of β cell function may offer the potential to counteract the detrimental glucometabolic effects of DIO without the risk of causing hypoglycaemia or unwanted body weight gain." (PMID 38418586, 2024). "A patient had hypoglycemia symptoms during dialysis, due to the delay in CGM detection, the insulin dose could not be adjusted in time, which may lead to aggravated symptoms." (PMID 39628691, 2024). "In the multinational and multicenter DREAM project and other studies conducted in camps, patients treated with an HCLS had less nocturnal hypoglycemia and better glycemic control, with a reduction in TBR and TAR compared to non-automated insulin delivery systems." (PMID 39064653, 2024). "Individuals who had post-bariatric surgery hypoglycaemia had greater postprandial GLP-1 and insulin concentrations, but GIP responses were not different, when compared with individuals who had the same type of bariatric surgery but who did not develop hypoglycaemia." (PMID 37439960, 2023). "Intranasal insulin (INI) administration of up to 160 units in patients with cognitive dysfunction and delirium has been shown to improve memory function and brain metabolism without hypoglycemia." (PMID 38129907, 2023).
Hypoglycemia (continued). "For nocturnal non-severe hypoglycemia, the RRR was 39% for treatment with insulin analogs corresponding to an ARR of 4.2 events per patient-year (p < 0.0001), and when divided into asymptomatic and symptomatic nocturnal hypoglycemia, the RRR was 28% (p < 0.001) and 48% (p < 0.0001), respectively." (PMID 38089060, 2023). "The concomitant presence of AD and T1DM leads to hypoglycemic episodes due to reduced gluconeogenesis and greater insulin sensitivity; clinicians should thus rule out a potential AD onset in patients with T1DM suffering from unexplained recurrent hypoglycemia and fatigue." (PMID 36980146, 2023). "Another case study reported the occurrence of hypoglycemia and GD in a non-diabetic patient with the DRB1*0406 gene, in whom the total insulin normalized and no other episodes of hypoglycemia occurred following discontinuation of methimazole and prescription of PTU." (PMID 37519546, 2023). "As model of IAH, recurrent antecedent treatment with 2-deoxyglucose (2DG) blunted the food intake response to insulin-induced hypoglycemia; yet rodents treated with carvedilol did not develop IAH (i.e., did not exhibit a blunted food intake response to hypoglycemia)." (PMID 37942482, 2023). "Interestingly, the frequency of hypoglycaemia in patients with T2DM did not change significantly in TC, although insulin and sulfonylureas were used less frequently during the study period." (PMID 36768000, 2023). "The COMBO and a mobile applicative (GLIC) bolus calculator had a similar and a good performance to optimize the intensive insulin treatment of T1D in the public health system with increase in the TIR and reduction in A1C without increase hypoglycemia prevalence." (PMID 36100854, 2022). "Generally, this study highlights the extent of hypoglycemia and rate of glycemic control using real-world data among patients initiated with NPH and premixed insulin regimens, which is not demonstrated before in resource-limited settings, particularly in the study area." (PMID 36149907, 2022). "Therefore, caution should be taken when interpreting hypoglycemia, which is likely related to differences between pump users and MDI users rather than the insulin delivery modality." (PMID 35757419, 2022). "For the subgroups with HbA1c <7% and 7% ≤ HbA1c ≤ 9%, patients who use premixed insulin have a higher IA level, the TIR was not higher than patients in the basal insulin group, however the incidence of hypoglycaemia and GV were both higher in premixed insulin group." (PMID 35574003, 2022). "Insulin has previously shown anti-inflammatory properties by increasing IL-4, IL-13 and Il-10 production and decreasing IFN-γ production in injuries, with no adverse events or indications of hypoglycemia." (PMID 35456892, 2022). "However, the exact mechanism by which ADCY7 leads to excessive insulin secretion through GSIS is still not explained by only increasing SLC2A2 and GCK expression during hypoglycemia conditions." (PMID 34177802, 2021). "Indeed, the extent of hypoglycemia was similar in the SHAM and CHADN groups (~45 mg/dl) for the same amount of circulating insulin (~50 μU/ml) regardless of time or surgery." (PMID 33769710, 2021). "In this study, there were no episodes of hypoglycaemia related to advice from the closed-loop algorithm, but the use of the CGM highlighted clinically silent episodes of hypoglycaemia in both study arms, independent of insulin use." (PMID 31399480, 2020). "However, unlike insulin, studies in rodents and primates showed that FGF21 normalizes blood glucose levels without inducing hypoglycemia even at a very high dose (i.e., there is a ceiling effect by which FGF21 decreases blood glucose no further)." (PMID 30802174, 2019). "Insulin secretagogues have been widely used for managing T2DM; however, because the drug triggers insulin secretion irrespective of glucose concentrations, iatrogenic hypoglycemia remains an impediment." (PMID 31018587, 2019).
Hypoglycemia (continued). "Hypoglycemia has a significant negative impact on a person’s well-being and QOL and can therefore influence adherence, compliance, and ultimately the success of the insulin therapy." (PMID 29508275, 2018). "Regarding T2DM, non-severe hypoglycemia seems to occur less frequently (0.2 to 48.0 events per patient-year) but, like in T1DM, may increase with longer duration of insulin therapy." (PMID 30479669, 2018). "This makes us understand that the indications of insulin therapy in T2DM should be more proactive, albeit not at the cost of severe symptomatic hypoglycemia, especially in patients where hypoglycemia may be deleterious." (PMID 29527102, 2018). "Another recent post hoc analysis examined whether Glar-300 could provide insulin-naïve patients on OADs with reductions in prior OAD therapy without compromising impact on HbA1c, while preserving the hypoglycemia benefit of Glar-300 versus Glar-100." (PMID 29619381, 2018). "The infrequency of insulin-providing agents and DPP-4 inhibitors in the good GC subgroup than in others may contribute to the tight GC without hypoglycemia." (PMID 29545773, 2018). "Using the LOGIC-Insulin algorithm improved the quality of BGC reflected by a reduction in the GPI, an increase in time-in-target range and a reduction in blood glucose variability, without increasing the incidence of hypoglycemia." (PMID 28806982, 2017). "Patients may be switched from insulin NPH to long-acting analogues if the intended level of HbA1c could not be reached due to hypoglycaemia episodes, or hypoglycaemias are occurring regardless of HbA1c." (PMID 28582404, 2017). "In early humans, exercise-induced hypoglycemia could be lethal as it would impede escape from a predator; the absence of MCT1 ensures insulin secretion remains switched off during exercise." (PMID 25982967, 2015). "However, while insulin-hypoglycemia increased VMH ROS production by 50% in control rats, insulin-hypoglycemia did not significantly increase VMH ROS levels in NAC treated rats." (PMID 23894333, 2013). "While the absolute reduction in HbA1c is comparable between the insulin pump and MDI groups at year 5, we did not capture indices of glycaemic variability, which include fluctuations in day‐to‐day glucose such as glucose flux in recovery from hypoglycaemia and post‐prandial rises." (PMID 40390300, 2025). "At present, the diagnosis of IAS requires the following conditions: high hyperinsulinemic hypoglycemia, with significantly elevated insulin levels (usually higher than 100 μIU/ml); blood glucose levels below 2.8 mmol/L; elevated IAA levels; and the absence of exogenous insulin administration." (PMID 41234224, 2025). "Given the reduction in basal insulin doses without change in HbA1c, we hypothesize that insulin dose reduction and sulfonylurea discontinuation may have been recommended in response to previously unrecognized CGM-detected hypoglycemia." (PMID 40799672, 2025). "Among the different approaches to insulin therapy, the continuous-rate infusion (CRI) of regular insulin has gained widespread use due to its ability to provide stable plasma insulin concentrations and facilitate a gradual reduction in blood glucose levels without triggering hypoglycemia." (PMID 41150108, 2025). "For these reasons, it is essential to avoid hypoglycemia during HHC, and it is recommended that glucose should not be lowered below 200–300 mg/dL during the first few hours of treatment, which takes place during the initial intravenous insulin therapy phase (IIITP)." (PMID 38594758, 2024). "Therefore, we conducted this cohort study to compare the outcomes of all-cause mortality, hospitalization for COPD, bacterial pneumonia, ventilator use, lung cancer, and severe hypoglycemia in people with coexisting T2D and COPD with or without receiving insulin therapy." (PMID 37242426, 2023).